TRBV10-1 (T cell receptor beta variable 10-1)
Description:
V region of the variable domain of T cell receptor (TR) beta chain that participates in the antigen recognition. Alpha-beta T cell receptors are antigen specific receptors which are essential to the immune response and are present on the cell surface of T lymphocytes. Recognize peptide-major histocompatibility (MH) (pMH) complexes that are displayed by antigen presenting cells (APC), a prerequisite for efficient T cell adaptive immunity against pathogens. Binding of alpha-beta TR to pMH complex initiates TR-CD3 clustering on the cell surface and intracellular activation of LCK that phosphorylates the ITAM motifs of CD3G, CD3D, CD3E and CD247 enabling the recruitment of ZAP70. In turn ZAP70 phosphorylates LAT, which recruits numerous signaling molecules to form the LAT signalosome. The LAT signalosome propagates signal branching to three major signaling pathways, the calcium, the mitogen-activated protein kinase (MAPK) kinase and the nuclear factor NF-kappa-B (NF-kB) pathways, leading to the mobilization of transcription factors that are critical for gene expression and essential for T cell growth and differentiation. The T cell repertoire is generated in the thymus, by V-(D)-J rearrangement. This repertoire is then shaped by intrathymic selection events to generate a peripheral T cell pool of self-MH restricted, non-autoaggressive T cells. Post-thymic interaction of alpha-beta TR with the pMH complexes shapes TR structural and functional avidity.
Synonyms: TRBV101; TCRBV10S1; TCRBV12S2A1T; TCRBV12S2
Gene: T-cell receptor variable (V) gene on chromosome 7 (142,399,860 to 142,400,377, forward strand). Ensembl gene ENSG00000211717.
Subcellular location: Cell membrane
Gene Ontology:
Biological process: cell surface receptor signaling pathway
Cellular component: plasma membrane
Homologues: Orthologues: chimpanzee TRBV10-1 (82% identical), macaque TRBV10-1 (77% identical), mouse Trbv13-2 (60% identical), mouse Trbv13-3 (60% identical), mouse Trbv13-1 (58% identical). Paralogues in human: TRBV10-3 (83% identical), TRBV10-2 (82% identical), TRBV6-4 (63% identical), TRBV6-5 (59% identical), TRBV6-7 (59% identical), TRBV6-6 (58% identical), TRBV6-1 (56% identical), TRBV6-2 (56% identical), TRBV6-8 (56% identical), TRBV24-1 (54% identical), TRBV27 (54% identical), TRBV25-1 (54% identical), and 39 more.
Diseases named in the same sentence as TRBV10-1 in open-access papers:
TRBV10-1 is named in the same sentence as 1 disease in open-access papers, as found by Europe PMC text mining. Sharing a sentence is not in itself a finding about the gene and the disease.
TRBV10-1 shares sentences with these, for which no sentence is quoted: tumor (1 paper).